LRRC8A (leucine rich repeat containing 8 VRAC subunit A)
Diseases named in the same sentence as LRRC8A in open-access papers (continued):
Sharing a sentence is not in itself a finding about the gene and the disease.
Stroke (6 papers, 2020 to 2026). Sudden impairment of blood flow to a part of the brain due to occlusion or rupture of an artery to the brain. "Studies have shown that blocking VRACs with DCPIB or conditionally knocking out LRRC8A in astroglial cells can alleviate ischemic brain injury and improve the prognosis for stroke patients." (PMID 41439137, 2026). "Mice with astrocyte‐specific or whole‐brain deletion of LRRC8A develop significantly smaller infarcts in experimental stroke models." (PMID 35150591, 2022). "Astroglial LRRC8A is also required for stroke-induced brain damage, because conditional knockout of LRRC8A protected from ischemic stroke." (PMID 33511120, 2020). "In summary, extensive research highlights the crucial role of LRRC8A, an essential component of VRACs, in central nervous system conditions such as epilepsy and stroke, suggesting it as a promising target for therapeutic interventions in neurological disorders." (PMID 41439137, 2026).
colorectal cancer (5 papers, 2019 to 2026). A primary or metastatic malignant neoplasm that affects the colon or rectum. "In colorectal cancer, LRRC8A interacts with PIP5K1B to promote PIP2 (phosphatidylinositol-bisphosphate) production." (PMID 41439137, 2026). "Very recently, LRRC8A proteins were found highly expressed in hematogenous metastasis from human colorectal cancer samples." (PMID 38909013, 2024). "LRRC8A proteins were found highly expressed in hematogenous metastasis from human colorectal cancer samples." (PMID 38909013, 2024).
ovarian carcinoma (5 papers, 2018 to 2022). A malignant neoplasm originating from the surface ovarian epithelium. "The available studies indicated, that in cisplatin sensitive human ovarian carcinoma cells (wild-type (WT)), cisplatin-induced osmolyte loss correlates with increased LRRC8A expression, while cisplatin resistance in A2780 RES cells correlates with decreased LRRC8A expression." (PMID 35054564, 2021). "The potential relevance to the treatment of human cancer is suggested by our finding that patients with ovarian cancer as well as HNSCC with low gene expression levels of LRRC8A or LRRC8D in their tumors have a reduced benefit of Pt-based chemotherapy." (PMID 36467895, 2022). "Another group concluded that cisplatin uptake in human ovarian cancer cells (A2780) depends on the presence of the LRRC8A subunit and is sensitive to volume changes and that cisplatin resistance of these cells is associated with decreased LRRC8A expression." (PMID 35054564, 2021). "Inhibition of LRRC8A could effectively attenuate cancer drug resistance in glioma and ovarian cancer cells." (PMID 33614474, 2020). "Furthermore, they found that a low expression of LRRC8D, not LRRC8A, was correlated with shorter survival of ovarian cancer patients treated with platinum-based drugs." (PMID 30071606, 2018).
Cerebral ischemia (4 papers, 2022 to 2024). Restriction of arterial blood supply to the brain associated with insufficient oxygenation to support the metabolic requirements of the tissue. "Indeed, not only was mature microglial morphology established without LRRC8A, but these cells were equally capable of transformation to reactive morphologies following cerebral ischemia." (PMID 35150591, 2022).
cervical cancer (4 papers, 2023 to 2026). A primary or metastatic malignant neoplasm involving the cervix. "In cervical cancer, destabilizing LRRC8A mRNA through NSUN2 inhibition or directly antagonizing LRRC8A function could reactivate apoptotic pathways." (PMID 41439137, 2026). "In cervical cancer, the RNA methyltransferase NOL1/NOP2/Sun domain family member 2 (NSUN2) stabilizes LRRC8A mRNA through m5C modification, activating the PI3K-AKT signaling pathway, which ultimately suppresses cell apoptosis and facilitates tumorigenesis." (PMID 41439137, 2026).
Hypertension (4 papers, 2021 to 2025). The presence of chronic increased pressure in the systemic arterial system. "More importantly, using the LRRC8A transgenic mice, we found that overexpression of LRRC8A in smooth muscle cells further exacerbated hypertension‐induced vascular remodeling in Angiotensin II infusion models." (PMID 34725866, 2021). "Taken together, these results suggested that smooth muscle specific overexpression of LRRC8A aggravated cerebrovascular vascular remodeling during Angiotensin II‐induced hypertension." (PMID 34725866, 2021). "Our results revealed that the expression of LRRC8A was progressively increased during the development of hypertension, accompanied by the activation of WNK1." (PMID 34725866, 2021). "Similar to the relation between VRAC activity and cerebrovascular remodeling during hypertension, our results demonstrated that the expression of LRRC8A was positively correlated with rat basilar artery remodeling during the development of hypertension in 2k2c hypertension models." (PMID 34725866, 2021). "Whether downregulation of LRRC8A would ameliorate hypertension‐induced cerebrovascular vascular remodeling can be determined using a smooth muscle‐specific knockout model in the further studies." (PMID 34725866, 2021). "During the challenge of hypertension, the activated LRRC8A channel‐mediated‐Cl− efflux increases WNK1 phosphorylation, which in turn triggers AKT phosphorylation and promotes BASMCs proliferation, eventually exacerbates hypertension‐induced cerebrovascular vascular remodeling." (PMID 34725866, 2021). "Smooth muscle specific overexpression of LRRC8A increases BASMCs proliferation and substantially aggravates basilar artery remodeling, revealing a potential therapeutic target for vascular remodeling in hypertension." (PMID 34725866, 2021). "The primary goal of this study was to elucidate the role of LRRC8A in VRAC activity in VSMCs and the functional role of LRRC8A in cerebrovascular remodeling during hypertension." (PMID 34725866, 2021).
ischemia (4 papers, 2020 to 2024). A hypoperfusion of the BLOOD through an organ or tissue caused by a PATHOLOGIC CONSTRICTION or obstruction of its BLOOD VESSELS, or an absence of BLOOD CIRCULATION. "On the other hand, ischemia-induced brain infarct was found to be partially protected not only by astrocyte-specific Lrrc8a knockout presumably by suppressing excitotoxicity but also by neuron-targeted Lrrc8a disruption presumably through inhibition of apoptosis induction." (PMID 35002778, 2021).
metabolic syndrome (4 papers, 2022 to 2026). A cluster of metabolic risk factors for CARDIOVASCULAR DISEASES and TYPE 2 DIABETES MELLITUS. "Ultimately, developing LRRC8A-targeted metabolic modulators represents a promising strategy for treating metabolic syndrome and related disorders." (PMID 41439137, 2026).
non-alcoholic fatty liver disease (4 papers, 2022 to 2026). "Similarly, important is the investigation of the contribution of LRRC8A to hepatic metabolic dysregulation, particularly in non-alcoholic fatty liver disease, as this will enhance our understanding of its regulatory effects on lipid homeostasis, oxidative stress, and inflammatory pathways." (PMID 41439137, 2026).
ischemic stroke (3 papers, 2020 to 2026). A stroke disorder caused by obstruction of blood flow to the brain, due to thrombotic (local blood clot formation) or embolic (due to a blood clot or other material traveling from another site) event. "Previous studies have reported that LRRC8A is associated with neurological disorders such as epilepsy and ischemic stroke." (PMID 41439137, 2026).
lung carcinoma (3 papers, 2016 to 2024). "Our data clearly illustrate that downregulation/reduced translocation to the plasma membrane and activation of LRRC8A contribute to development of resistance against Cisplatin-induced apoptosis in ovarian and lung carcinoma cells." (PMID 26984736, 2016).
male infertility (3 papers, 2018 to 2025). The inability of the male to effect fertilization of an ovum after a specified period of unprotected intercourse. "Here we used Sertoli and germ cell–specific disruption of Lrrc8a to show that the male infertility observed in Lrrc8a−/− mice and ébouriffé mice, which express severely truncated LRRC8A proteins, is due to a loss of VRAC in germ cells." (PMID 29880644, 2018). "LRRC8A might be considered as new candidate gene for human male infertility, probably always associated with several other symptoms such like those of the severely affected Lrrc8a−/− and of ébouriffé mice." (PMID 29880644, 2018). "Our work shows that VRAC, probably through its role in cell volume regulation, is required in a cell-autonomous manner for proper sperm development and explains the male infertility of Lrrc8a−/− mice and the spontaneous mouse mutant ébouriffé." (PMID 29880644, 2018). "To identify the cell type in which absence of LRRC8A causes male infertility, we generated different conditional LRRC8A knock-out (KO) mouse models." (PMID 29880644, 2018). "Here we show that germ cell–specific, but not Sertoli cell–specific, disruption of Lrrc8a leads to abnormal sperm and male infertility in mice." (PMID 29880644, 2018).
cholangiocarcinoma (2 papers, 2018 to 2024). A carcinoma that arises from the intrahepatic biliary tree (intrahepatic cholangiocarcinoma) or from the junction, or adjacent to the junction, of the right and left hepatic ducts (hilar cholangiocarcinoma). "We obtained in vivo evidence for deregulation of this tumor suppressive mechanism in human cholangiocarcinomas, where several genes involved in taurine-mediated volume regulation (GABRB3, PANK1 and LRRC8a) were repressed." (PMID 29787571, 2018). "Microarray-based expression profiling of 104 resected human cholangiocarcinomas revealed reduced expression of GABRB3, PANK1, and LRRC8A, but not GABRA5 or ADO, compared to micro-dissected bile duct controls." (PMID 29787571, 2018). "Stratifying the cohort of 104 cholangiocarcinomas for RNA expression above and below the mean revealed that low RNA expression of GABRA5, LRRC8a, ADO and PANK1, but not GABRB3, was associated with reduction of the median survival time of patients by 1.8, 2.1, 3.3, and 4.3 years, respectively." (PMID 29787571, 2018).
deafness (2 papers, 2024 to 2025). An inherited or acquired condition characterized by the complete loss of the ability to hear from one or both ears. "LRRC8A deficiency disrupts cell volume control, impairs auditory sensitivity, and causes deafness, while targeted LRRC8A re‐expression restores auditory function." (PMID 40642832, 2025). "Targeted disruption of the obligatory VRAC subunit LRRC8A in the inner ear led to deafness followed by progressive degeneration of the OC." (PMID 38838775, 2024).
epilepsy (2 papers, 2022 to 2026). A brain disorder characterized by episodes of abnormally increased neuronal discharge resulting in transient episodes of sensory or motor neurological dysfunction, or psychic dysfunction. "LRRC8A is predominantly up-regulated in astrocytes located around lesions in epilepsy patients." (PMID 41439137, 2026).
glioma (2 papers, 2020). A benign or malignant brain and spinal cord tumor that arises from glial cells (astrocytes, oligodendrocytes, ependymal cells). "Also, temozolomide resistance was found to be associated with downregulation of LRRC8A in glioma cells." (PMID 33511120, 2020). "Overexpression of LRRC8A was also observed to augment apoptosis induced by another anti-cancer drug, temozolomide, in glioma cells." (PMID 33511120, 2020).
Glucose intolerance (2 papers, 2018 to 2020). Glucose intolerance (GI) can be defined as dysglycemia that comprises both prediabetes and diabetes. "Skeletal muscle-targeted Lrrc8a ablation increases adiposity and induces glucose intolerance with overnutrition." (PMID 32930093, 2020).
Infertility (2 papers, 2017 to 2022). "Lrrc8a KO mice are severely compromised and show an increased mortality in utero and postnatally, as well as infertility." (PMID 36467895, 2022). "Ebo/ebo mice share features with LRRC8A-/- mice that include curly hair, infertility, reduced longevity, and kidney abnormalities." (PMID 28553230, 2017).
overnutrition (2 papers, 2020 to 2023). An imbalanced nutritional status resulting from excessive intake of nutrients. "In vivo, LRRC8A is required for maintaining normal exercise capacity, muscle endurance, adiposity under basal conditions, and systemic glycemia in the setting of overnutrition." (PMID 32930093, 2020). "Finally, using skeletal muscle Lrrc8a knock-out mice, we reveal the requirement of skeletal muscle LRRC8A for maintaining normal skeletal muscle cell size, muscle endurance, force generation, adiposity and glucose tolerance, under basal conditions and in the setting of overnutrition." (PMID 32930093, 2020).
pancreatic adenocarcinoma (2 papers, 2022 to 2024). "Patients with high LRRC8A levels had a significantly worse prognosis in cases of COAD, Head-Neck Squamous Cell Carcinoma (HNSC), and Pancreatic adenocarcinoma (PAAD)." (PMID 38909013, 2024).
Azoospermia (1 paper, 2021). Absence of any measurable level of sperm,whereby spermatozoa cannot be observed even after centrifugation of the semen pellet. "Disruption of Clcn2 causes azoospermia, whereas loss of Lrrc8a results in abnormal, immotile spermatozoa." (PMID 33187987, 2021).
heart failure (1 paper, 2022). Inability of the heart to pump blood at an adequate rate to meet tissue metabolic requirements. "LRRC8A inhibition might be a promising strategy for cardiac fibrosis and heart failure." (PMID 35966575, 2022).
Hyperkeratosis (1 paper, 2025). Hyperkeratosis is a histopathological term defining a thickened stratum corneum and may be present in many different skin conditions, with many possible overlaps. "A LRRC8A-knockout mouse model shows epidermal hyperkeratosis, indicating severe defects in the absence of LRRC8A in vivo." (PMID 40492178, 2025).
immune deficiencies (1 paper, 2025). "Genetic variants in LRRC8A and other LRRC8 subunits, such as LRRC8C have been identified in human populations and are primarily associated with immune deficiencies and developmental disorders." (PMID 40299635, 2025).
inflammatory skin disease (1 paper, 2025). Inflammatory skin disorders covers a broad category that includes many conditions ranging in severity, from mild itching to grave medical health complications These disorders are common in people of all ages and races. "Since PI3K/AKT signaling is involved in keratinocyte differentiation and is hyperactivated in various inflammatory skin diseases like psoriasis, it may link LRRC8A to epidermal differentiation." (PMID 40492178, 2025).
lymphopenia (1 paper, 2024). Reduction in the number of lymphocytes. "Additionally, to eliminate the potential impact of external factors on LRRC8A-/- mouse lymphopenia, the authors generated a chimeric LRRC8A-/-→Rag2-/- mouse model by transplanting LRRC8A-/- bone marrow cells into Rag2-/- mice, that do not produce T and B lymphocytes." (PMID 39113714, 2024).
lysosomal disorders (1 paper, 2019). "As a result of this preliminary screen, disruptive variants in C10orf35, LRRC8A and MARCH7 found by clinical sequencing should be considered candidate genes for neuromuscular and lysosomal disorders of unknown origin." (PMID 31270356, 2019).
Myocardial fibrosis (1 paper, 2022). "From the translational perspective, these results reveal the therapeutic role of LRRC8A inhibition in attenuating myocardial fibrosis and HF." (PMID 35966575, 2022). "To test the hypothesis of whether LRRC8A regulates myofibroblast phenotypes and myocardial fibrosis, we first determined the effect of MI on cardiac LRRC8A expression." (PMID 35966575, 2022). "Leucine-rich repeat-containing protein-8A (LRRC8A) is a multi-functional protein involved in cell survival, growth, and proliferation, whereas its role in regulating myofibroblast phenotypes and myocardial fibrosis remains unknown." (PMID 35966575, 2022).
myocardial ischemia (1 paper, 2022). A disorder of cardiac function caused by insufficient blood flow to the muscle tissue of the heart. "Considering the significance of LRRC8A in controlling cell fate and phenotypes, we proposed that LRRC8A may participate in myofibroblast phenotypes and cardiac fibrotic remodeling in response to insults such as myocardial ischemia." (PMID 35966575, 2022).
open-angle glaucoma (1 paper, 2019). Chronic outflow obstruction of the eye's drainage canals that can lead to increased internal eye pressure and optic nerve damage. "Interestingly, LRRC8A protein was significantly diminished by 32.65 ± 1.61% in primary HTM cells derived from patients with open-angle glaucoma (Ind." (PMID 30931966, 2019).
pancreatic cancer (1 paper, 2026). "Research on pancreatic cancer has revealed that the influence of LRRC8A extends beyond its intrinsic effects on cancer cells to the tumor microenvironment." (PMID 41439137, 2026). "For pancreatic cancer, LRRC8A inhibition presents the intriguing possibility of converting an immunosuppressive microenvironment to an immunopermissive one, potentially synergizing with checkpoint inhibitor immunotherapies." (PMID 41439137, 2026). "Although the specific regulatory mechanisms remain unclear, this study suggests that LRRC8A contributes to immune evasion and creates a pro-tumor microenvironment, explaining why high LRRC8A expression serves as a negative prognostic indicator for pancreatic cancer patients." (PMID 41439137, 2026).
pericardial effusion (1 paper, 2020). Fluid collection within the pericardial sac, usually due to inflammation. "Reduced csad level results in pericardial effusion, which is similar in lrrc8a morphants reported previously and in this study and can be rescued by taurine supplementation." (PMID 31941702, 2020). "Reduced csad level resulted in pericardial effusion, which is similar in lrrc8a morphants reported previously and in this study, and can be rescued by taurine supplementation." (PMID 31941702, 2020).
peritonitis (1 paper, 2020). Inflammation of the peritoneum (tissue that lines the abdominal wall and covers most of the organs in the abdomen). "We then used a murine peritonitis model described previously to investigate the role of LRRC8A in vivo." (PMID 33216713, 2020).
preeclampsia (1 paper, 2022). Preeclampsia is a hypertensive disorder of pregnancy that is characterized by new-onset hypertension with proteinuria presenting after 20 weeks of gestation, and depending on mild or severe forms may initially present with severe headache, visual disturbances, and hyperreflexia. "In addition, we showed that the facultative glucose transporter-3 (GLUT3) was overexpressed in PE; if LRRC27/42 functioned similarly as LRRC8A, both may operate in tandem with GLUT3 to enhance ‘resting state’ glucose entry in platelets and contribute to the prothrombotic tendency of preeclampsia." (PMID 35455936, 2022).